PCNX3 (pecanex 3)
Synonyms: PCNXL3; FLJ22427
Tractability: Antibody: UniProt predicts a signal peptide or a membrane-spanning region. PROTAC: ubiquitination databases record sites on it.
Gene: Protein-coding gene on chromosome 11 (65,615,754 to 65,637,441, forward strand). Ensembl gene ENSG00000197136.
Subcellular location: Membrane
Subcellular location (Human Protein Atlas): Cytosol
Gene Ontology:
Molecular function: protein binding
Cellular component: membrane
Genetic constraint (gnomAD): Loss-of-function variants: 58 observed, 182.54 expected, observed/expected ratio (o/e) 0.32, 90% interval 0.26 to 0.4. The synonymous counts are far from expectation, so gnomAD's model fits this gene poorly and the ratio says little. Missense variants: 2,410 observed, 2,656.5 expected, observed/expected ratio (o/e) 0.91, 90% interval 0.88 to 0.94. Synonymous variants: 1,337 observed, 1,140.3 expected, observed/expected ratio (o/e) 1.17, 90% interval 1.12 to 1.23.
Homologues: Orthologues: chimpanzee PCNX3 (99% identical), macaque PCNX3 (99% identical), pig PCNX3 (96% identical), dog PCNX3 (96% identical), guinea pig PCNX3 (95% identical), rat Pcnx3 (95% identical), mouse Pcnx3 (95% identical), zebrafish pcnx3 (66% identical), Drosophila melanogaster pcx (40% identical), Caenorhabditis elegans B0511.12 (32% identical). Paralogues in human: PCNX1 (53% identical), PCNX2 (43% identical), PCNX4 (11% identical).
Diseases named in the same sentence as PCNX3 in open-access papers:
PCNX3 is named in the same sentence as 6 diseases in open-access papers, as found by Europe PMC text mining. Sharing a sentence is not in itself a finding about the gene and the disease. The quoted sentences say what the papers report.
gout (1 paper, 2024). A condition characterized by painful swelling of the joints, which is caused by deposition of urate crystals. "The genes MAP3K11, KRTCAP2, and PCNX3 influence the function of macrophages, plasma cells, and MDCs, respectively, to increase gout risk." (PMID 38831441, 2024). "Specifically, KRTCAP2, as a keratin-associated protein, may play a key role in maintaining the structure and function of immune cells such as macrophages and neutrophils, while PCNX3 may influence the progression of gout inflammation by regulating cellular responses to inflammatory signals." (PMID 38831441, 2024). "Finally, we found by single-cell analysis that MAP3K11, KRTCAP2, PCNX3, and TM7SF2 demonstrate potential significant roles in the pathogenesis of gout." (PMID 38831441, 2024). "Although the precise roles of KRTCAP2 and PCNX3 in gout are not fully clear, their biological functions suggest they may indirectly participate in the pathological process of gout through affecting cellular skeletal stability, cell signaling, and stress responses." (PMID 38831441, 2024).
hyperuricemia (1 paper, 2018). An abnormally high level of uric acid. "Of these SNVs, nine are located at seven gene loci (DDX39B, NFKBIL1, CDC42BPG, CDC63, BRAP, ACAD10, and PCNX3) that might be novel susceptibility loci for hyperuricemia." (PMID 29124443, 2018).
PCNX3 also shares sentences with these, for which no sentence is quoted: tumor (3 papers); cancer (2); colon adenocarcinoma (1); colon adenoma (1).